TNF (tumor necrosis factor)
Diseases named in the same sentence as TNF in open-access papers (continued):
Sharing a sentence is not in itself a finding about the gene and the disease.
infection (continued). "HNP-1 has been shown to act as a chemotactic factor for both macrophages and T lymphocytes and HNP-1 treatment enhances leukocyte accumulation at the site of infection in K. pneumonia-infected mice and provokes TNF-α release from lymphocytes." (PMID 24147170, 2013). "The infection of BMM with mycobacteria induces TNF-alpha production, a cytokine that (specifically) induces the expression of H-ferritin by an increase in Fth1 transcription." (PMID 24349383, 2013). "Here, we further analysed the respective roles of IL-1α and IL-1β, as compared with TNF in host response to infection by virulent M. tuberculosis but also attenuated M. bovis BCG." (PMID 25400917, 2013). "In this study, analysis from C. trachomatis infected macrophages revealed increased levels of GM-CSF, IL-1α, IL-1β, IL-6, TNF, IL-12p70, and IL-10 after a 2-day infection, with TNF, IL-6, and IL-1α being more robustly produced." (PMID 23766556, 2013). "Since IL-6 mediated, at least in part, the inhibition of TNF and IL-12 secretion by SOCS3-deficient BMM and BMDC, the role of IL-6 in the susceptibility of gp130F/F mice to infection with M. tuberculosis was studied." (PMID 23853585, 2013). "The percentage of TNF-α producing monocytes increased after infection from 11.5± % to 47.2±5.6% 4 hours p.i.." (PMID 23349721, 2013). "The appearance of an increase in the frequencies of pDCs that synthesize TNF-α at the end of the acute infection period, similarly, has poor prognostic outcome." (PMID 23620737, 2013). "The infection of J774A.1 macrophages resulted in an increase in TNF-α, IL-1β, and IL-6 expression; IL-10 was downregulated during Leishmania infection, although its expression recovered compared to noninfected macrophages." (PMID 23555077, 2013). "In the absence of CXCR3, we found that lamina propria neutrophil levels were increased during infection, as was their activation status as measured by TNF-α expression." (PMID 24130498, 2013). "We have demonstrated previously that, unless overwhelming doses of Brucella are injected (>108 CFUs), TNF-α, IL-6 and IL/-10 cytokines seldom reach significant levels in serum at early times of infection." (PMID 23458832, 2013). "IFN-α produced by A549 cells after RSV or hMPV infection remained undistinguishable, whereas production of TNF-α was significantly higher after RSV infection than hMPV infection either in the presence or absence of Poly I:C." (PMID 24039959, 2013). "We also observed that treatment with IL-10 significantly inhibited the expression of TNF-α and IL-6 induced by infection." (PMID 24260222, 2013). "Infection with influenza virus, a major ssRNA virus, induces a significant increase in the production of TNF-α and IL-6 by macrophages, leading to enhanced inflammatory responses." (PMID 24191131, 2013). "TNF levels following infection are only increased in the bgh mutant, further suggesting that the immune response is more severe in the bgh mutant than the nm1054 mutant." (PMID 24360193, 2013). "Several reports have also shown that a variety of proinflammatory cytokines can overcome Treg suppression during infection or in an inflamed environment, including IL-2, IL-4, IL-6, and TNF-α." (PMID 23593527, 2013). "The production of IFN-γ, TNF-α, and IL-12p70, increased to a statistically significant level in the S. rugosus-infected mice compared with S. rotundus-infected mice at 5 days post-infection." (PMID 23555735, 2013). "To investigate differential inflammatory responses associated with Lmo-InlA-mur-lux and Lmo-EGD-lux infections, we measured serum levels of IFN-γ, IL-10, TNF-α, IL-6, CCL2, IL-5 and IL-1β at 3 and 5 days p.i. using Luminex bead arrays." (PMID 23617550, 2013). "This was associated with increased development of cellular immunity and enhanced synthesis of TNF-α which enhances cell migration to the site of infection and contributes to the better organization of lesions." (PMID 23936574, 2013).
infection (continued). "Previous studies characterizing NLRP12 in human monocyte cell lines revealed that NLRP12 functions as a negative regulator of NF-κB signaling following stimulation with TLR agonist, TNFα and infection with M. tuberculosis." (PMID 23577168, 2013). "A 2009 study to assess the prevalence of serious infections among RA patients receiving anti-TNF therapy found that 20.5 percent of the serious infections identified were SSSTI." (PMID 24498926, 2013). "TNF-α inhibits IRS-1, GLUT4 and adiponectin in TNF-α-treated control cells, however, infection with Ad:IGFBP-3 restored IRS-1, GLUT4 and adiponectin mRNA and protein levels." (PMID 23383064, 2013). "Cytokines measurements in lung homogenates at week 2 after infection demonstrated that, although anti-TNF-α treatment remained until day 12 postinfection, TNF-α rapidly reached the pre-treatment levels in the liver and lungs of both mouse strains." (PMID 23936574, 2013). "SOCS3-deficient BMM showed increased STAT3 activation and diminished secretion of TNF and IL-12 after infection with either M. tuberculosis or BCG." (PMID 23853585, 2013). "The cellular responses to a culture filtrate protein of Mtb however is generally a slowly evolving one and gradually builds up (IL-2, IL-5, IFN-γ and TNF-α) over the course of infection with M. ulcerans (right column)." (PMID 23516649, 2013). "From these, 3 cytokines (TNF-α, IL-6, and KC) were already elevated early at 1 hour after infection and remained elevated at 17 and 48 hours after infection." (PMID 23520553, 2013). "We analysed the relationship between cord levels of the cytokines IL-1β and TNF-α, and parasite densities during subsequent infections." (PMID 24130857, 2013). "One month after confirmed CA/09 infection, TNFα, IFNγ, and IL-2 responses against all peptide pools were higher in comparison to the unexposed cohort, and most of these increases were significant." (PMID 23526940, 2013). "TNFα and IL-6 levels were also comparable between the lungs of Nlrp12−/− and wild type mice at one day postinfection and during the chronic phase of the infection." (PMID 23577168, 2013). "TNF-α can promote inflammatory response by inducing the production of other proinflammatory cytokines at the vicinity of the infection, and increase the expression of endothelial surface HLA-B by activation of the nuclear transcription factor NF-κB." (PMID 23698783, 2013). "Inflammatory cytokines, including TNF-α, IL-1β and IL-6, can be released by activation of mononuclear macrophages after severe trauma, infection and shock." (PMID 24039865, 2013). "A mechanistic dissection revealed that LTA4H overexpression produces TNF excess during infection and can be rescued by genetic knockdown or pharmacological modulation of TNF." (PMID 23874453, 2013). "Supernatants were collected 48 hours post infection and the concentrations of TNF-α, IL-1β and IL-8 by ELISA were measured in multiple donors (N = 3)." (PMID 22727020, 2012). "We found that IL-1β, TNF-α and IL-12 levels were elevated in the brains of mice on day 6-post infection, and were reduced by lovastatin treatment." (PMID 23300448, 2012). "Several of the mediators that are essential to the immune response and activation of lymphocytes can exacerbate infection and cause clinical symptoms when over produced in response to HHV-8 infection, including IFN-γ, IL-1β, IL-6, IL-8, TNF-α, and MCP-1." (PMID 23346088, 2012). "In the current study, PR/8 infection induced an increase in TNF-α and IL-1β, well-known paracrine proinflammatory factors." (PMID 22396727, 2012). "To further characterise the modulation of TNFα by IE1 during infection we investigated the kinetics of TNFα production." (PMID 22952450, 2012). "Second, CD11b+CD11c− APCs generated following CB4 infection produce lower levels of the inflammatory cytokines TNF-α and IL-6." (PMID 22355341, 2012).
infection (continued). "Anti-TNF treatment administered early (beginning at 6 weeks post-infection) further significantly decreased NFATp−/− survival by 20 to 28 days (median survival for NFATp−/−+PBS mice was 145 vs. 117 for NFATp−/−+Enbrel mice; p = 0.003)." (PMID 22844476, 2012). "Although the wbbO mutants exhibited reduced lethality in the mouse model, the mutants stimulated the proinflammatory cytokine TNF-α to levels comparable to those resulting from infection with the wild-type strains." (PMID 22427976, 2012). "Serum levels of IL-12 and IFN-γ peaked early post-infection while TNF-α, IL-6 and IL-1β levels peaked later." (PMID 22545170, 2012). "Neutralization of TNF-α produced by mice chronically infected with M. tuberculosis specific monoclonal antibodies disrupts the integrity of granulomas, exacerbates infection, and increases mortality." (PMID 23251798, 2012). "Compared to each monospecies infection, polybacterial biofilms impaired all wound healing parameters (p<0.01), and increased expression of IL-1β and TNF-α (p<0.05)." (PMID 22905182, 2012). "We found significantly higher per-parasite levels of TNF-α in mixed-species symptomatic infections (median density, 228 parasites/μl) than in single-species symptomatic P. vivax infections (median density, 1184 parasites/μl)." (PMID 22973442, 2012). "In BLV replication, an important role for TNF-α has been suggested in the elimination of BLV during the early stage of infection and in the progression of disease during the lymphocytosis stage." (PMID 22455445, 2012). "The expression profiles of pro-inflammatory cytokines IL-6 and TNF-α in BALF after BJ501 infection were dramatically increased at 6 h." (PMID 22952892, 2012). "The results shows that the frequency of IFN-γ+ and TNF-α+ CD8+ T cells on day 5 post infection were comparable between WT and IL-10−/− mice." (PMID 22880122, 2012). "Infection of macrophages with bacteria induces the production of pro-inflammatory cytokines including TNF-α." (PMID 22723864, 2012). "The lack of this cytokine leads to reduced expression of immune mediators and increased susceptibility to primary infection with M. tuberculosis, and depletion of TNF after infection results in reactivation of latent disease." (PMID 23239994, 2012). "Neutrophil infection induced an IL-6 and TNF-α production that peaked 2 h after infection and declined thereafter." (PMID 22058091, 2012). "These toxic enzymes profoundly alter innate and adaptive immune responses that enable production of TNFα and other pro- and anti-inflammatory cytokines needed to fight infection." (PMID 22291977, 2012). "By contrast, at 16 weeks after infection, WT animals still appeared healthy and maintained lower TNF levels." (PMID 22844476, 2012). "For example, orally administered curcumin inhibited Klebsiella pneumoniae-induced neutrophil infiltration into lung tissue and local TNF-α production and diminished the production of proinflammatory proteins in a murine lung model of infection." (PMID 22431984, 2012). "Lipocalin 2 is an adipokine, whose secretion is highly regulated by activation of inflammation and infection, whereas lipopolysaccharide (LPS) and TNFα are two strong inducers of LCN2 production." (PMID 23285167, 2012). "Systemic TNF-α is enhanced during infection and appears to be crucial in the response against the parasite." (PMID 22461911, 2012). "CD8+ T-cells mediate protection against infection through the secretion of cytokines, such as IFNγ and tumor necrosis factor (TNF), and through CTL activity via the release of cytotoxic granules containing granzymes, granulysins and Pfn." (PMID 22532799, 2012). "A2AAR-/- and littermate wild-type (WT) mice were similarly infected, and IFNγ and TNFα were measured at peak of and recovery from infection." (PMID 23217055, 2012).
infection (continued). "Infection with different strains of H. pylori is recently shown to induce MSCs migration through TNF/NF-κB-dependent pathways in epithelial cells in vitro, therefore provide important link for the pathogenesis." (PMID 23217022, 2012). "The results indicate that TNF-α was rapidly induced in Salmonella-infected U937 cells starting at 1 hour after infection, and maximal production was reached at 8 h after infection with the two mutants." (PMID 22470519, 2012). "By 8 weeks post-infection, however, WT mice TNF mRNA levels were significantly higher than those observed in NFATp−/− mice." (PMID 22844476, 2012). "Increased protection correlated with an increased percentage of TB10.4 specific IFNγ/TNFα/IL-2 or TNFα/IL-2 producing CD4 T cells at the site of infection." (PMID 22768165, 2012). "The major mechanism by which these mice were able to control secondary infection was through increased production of TNF-α." (PMID 22007223, 2012). "The expression level of toll-like receptor 2 (Tlr2) and tumor necrosis factor (Tnf) of A/J mice after infection with SS2 were obviously upregulated." (PMID 22384161, 2012). "Three days after oral infection of adult zebrafish with Aeromonas hydrophila harboring pRAS1, elevated expression of pro-inflammatory cytokine (TNF α, IL-1β and IL-8) and complement C3 genes in the intestine coincided with disease symptoms." (PMID 22429905, 2012). "In attempts to focus more deeply on the impact of MT or BT infection on the T-cell cytokine pattern, we have characterized the frequency of TNF-α+, IFN-γ+ and IL-10+ T-cells as their major subsets (CD4+ and CD8+) within splenocytes." (PMID 22412949, 2012). "TNF-α promotes macrophage recruitment and factors in host response to infection with intracellular pathogens." (PMID 23092579, 2012). "In the process of control of the infection by mycobacteria, TNF-alpha seems to have a primordial function." (PMID 23251798, 2012). "The authors observed upregulation of TLR2 and TLR4 from day 1 to day 28 postinfection, and increased expression correlated with higher mRNA levels for TNFα, IL-17, IL-10, and TGFβ during early infection." (PMID 22523644, 2012). "During an active infection, TNF also enhances the recruitment of leukocytes to the site of infection and activates innate immune responses." (PMID 22792270, 2012). "IFNγ and TNFα levels were increased during infection in wild-type mice at both days 3 and 7 post-infection." (PMID 23217055, 2012). "Experiments using RNA interference provided evidence that in IFN-γ primed macrophages, TLR3 is required for the production of NO and TNF-α induced by infection with L. donovani, besides contributing to parasite phagocytosis." (PMID 22523644, 2012). "Serum TNF levels were also higher at 4 weeks post-TB infection in NFATp−/− mice relative to WT mice, and for both WT and NFATp−/− mice serum TNF levels rose at later time points, starting at 16 weeks post-infection, in the premortal stage of TB." (PMID 22844476, 2012). "We observed that FV3 infection of tadpoles elicited relatively modest (10–100 times lower than adults) and delayed (3 days later than adult frogs) up-regulation of TNFα, IL-1β, IFNγ and MX1 genes in peritoneal leukocytes and in infected tissues of tadpoles." (PMID 22852041, 2012). "Serum amounts of RANTES at 2 weeks infection were reduced in mutant mice, but at 4 weeks, levels were only lower in memTNFΔ1–12 KI and TNF−/− mice compared to wild-type mice." (PMID 22666310, 2012). "Together these data suggest that extended SchuS4 infection correlates with cessation of production of selected pro-inflammatory cytokines and chemokines, e.g. TNF-α, IL-6, MCP-1 and MIP-1α and continued production of IL-12p40 in target tissues." (PMID 22428026, 2012). "After infection, both bacteria produced endotoxins and various cytokines released by activated monocytes/macrophages such as TNFα, IL1β, IFNγ etc. can promote HMGB1 translocation from nucleus to cytoplasmic organelles." (PMID 22947457, 2012).
infection (continued). "TNF-α is the starting factor that mediates cell infiltration to a site of infection or tissue damage." (PMID 22203861, 2012). "After 1 and 2 hours after infection these mononuclear phagocytes produce TNFα and show an upregulated expression of genes coding for IL-1 and various chemokines and pattern recognition receptors such as toll-like receptors (TLRs)." (PMID 22481867, 2012). "Macrophages and neutrophils play a key role in the initial response to infection by secreting the cytokines IL-12, IL-18, and TNF-α." (PMID 22738332, 2012). "Our results identify differential effects of RANKL and TNF-α on osteoclastogenesis in RANKL-primed macrophages in the presence of pathogen, which will be useful in devising strategies to regulate bone loss in infection-induced inflammatory diseases." (PMID 22723864, 2012). "Mice that received 100 mg/kg of capsaicin showed decrease in BAL fluid IL-1β, IFN-γ and TNF-α concentration at 24 h post-infection (P = 0.007, 0.029 and 0.002, respectively)." (PMID 22427935, 2012). "More recent studies are beginning to suggest the ability of HCMV to suppress IL-1 and TNF-alpha signaling pathways at different times after infection." (PMID 22607552, 2012). "This question is important for understanding the roles of TNF-α produced by taste cells in pathological processes under noxious challenges including infection, injury, chemo- and radiotherapy, and stress." (PMID 22905218, 2012). "TNF-α also stimulates the migration of immune cells to the infection site, contributing to the granuloma formation, capable of controlling the disease progression." (PMID 23251798, 2012). "In vitro studies also indicate that infection, inflammation and inflammatory cytokines per se (e.g., TNF-α) downregulate hTERT enzyme activity, accelerating cell senescence." (PMID 22348044, 2012). "Results show that MCMV induced TNFα production after 4 days of infection in all organs tested, except in the heart." (PMID 22952450, 2012). "Acute inflammatory response is initiated following an infection through the production of proinflammatory cytokines, such as the tumor necrosis factor alpha (TNF-) and the interferon gamma (INF-) that play a prominent role in parasite destruction." (PMID 22479409, 2012). "The levels of CXCL1, CXCL10, CCL1, CCL3, IFN-γ, TNF-α and IL-6 were significantly increased in the lungs of RSV-infected IL-10-deficient mice compared to control mice on day 8 post infection." (PMID 22393401, 2012). "In the present study, the logistic regression analysis of cases and controls showed that TNF rs361525 (AA), rs1800750 (AA), and LTA rs909253 (AG) were associated with high risk of infection by pandemic influenza A/H1N1." (PMID 23148654, 2012). "There was a significant and gradual increase in TNF-α by 2.5-fold, 20-fold and 10-fold on 3 d, 5 d and 7 d post infection (d.p.i) respectively." (PMID 22393394, 2012). "Secretion of nitric oxide, IL-6, MCP-1, IFN-γ and TNF-α in ex vivo colon biopsies were significantly increased at day 12 following infection with C. jejuni ATCC 43431 or B2 versus naïve animals with supra-physiological intestinal E. coli loads." (PMID 22563475, 2012). "TNF is produced by monocytes and macrophages in early infection and plays a key role in protective immunity during tuberculosis infection." (PMID 22916219, 2012). "For these studies immunofluorescence staining monitored the intracellular production of TNFα while staining for viral early E1 antigen simultaneously monitored infection." (PMID 22952450, 2012). "The number of macrophages expressing TNF increased with the infection similarly in the three groups of mice." (PMID 22666310, 2012). "When an infection occurs, peripheral monocytes/macrophages respond with the secretion of inflammatory cytokines; among these IL-1, TNF-α and IL-6 seem to be the most important ones in mediating the cerebral response to infection." (PMID 23905041, 2012).